MCHR1 (melanin concentrating hormone receptor 1)
Diseases named in the same sentence as MCHR1 in open-access papers (continued):
Sharing a sentence is not in itself a finding about the gene and the disease.
Obesity (continued). "The presence of MCHR1 in BAT emphasizes its role in energy homeostasis and may open new possibilities for treatment of obesity." (PMID 33502798, 2021). "The melanin-concentrating hormone receptor 1 (MCHR1) has become an important pharmacological target, since it may be involved in various diseases, such as diabetes, insulin resistance, and obesity." (PMID 29948643, 2019). "Hence, a specific MCHR1 PET-tracer would provide deeper insights on the receptor’s involvement in lifestyle diseases, such as obesity and diabetes, and promote drug development for related pathologies." (PMID 29948643, 2019). "In mouse models of obesity, AMG 076 caused a reduction in body weight gain in wild-type (MCHR1+/+) but not in knockout (MCHR1−/−) mice." (PMID 25505557, 2013). "Unfortunately, although a few MCHR1 antagonists have entered development, no compound has successfully demonstrated anti-obesity efficacy in a clinical trial." (PMID 23626585, 2013). "None of the genotyped variants in genes for monogenic obesity reached genome-wide significance in our GWAS, although several variants in CRHR1, CRHR2, MCHR1, MC3R, MC4R and POMC were nominally associated." (PMID 23251661, 2012). "CNTNAP2, GLI2, DPT (dermatopontin), AEBP1, ITIH5, CXCL11, GDNF (glial cell derived neurotrophic factor), MCHR1, FLT3, ELANE (elastase, neutrophil expressed), OSMR (oncostatin M receptor) and IL15RA are involved in development of obesity, but these genes might be key for progression of HF." (PMID 34218797, 2021). "Moreover, we found that the anti‐obesity effect by compound‐A was not changed in Mchr1−/− mice and MCH expression was unchanged after compound‐A administration." (PMID 29568682, 2018). "Third, since humans also express MCHR2 in the hypothalamus, MCH signaling in humans may involve both MCHR1 and MCHR2, such that blockade of the MCHR1 alone may not be sufficient to achieve efficacy in obesity." (PMID 23626585, 2013). "Moreover, after more than a decade of drug discovery effort by more than 20 companies, there are currently no known MCHR1 antagonists in the clinic for obesity." (PMID 23626585, 2013). "However, Mchr1 knockout mice are lean, whereas MCH overexpression results in obesity." (PMID 23351214, 2013).
Anxiety (12 papers, 2011 to 2024). Intense feelings of nervousness, tension, or panic often arise in response to interpersonal stresses. "In addition to this role in sleep regulation, the MCH system and the MCH receptor 1 (MCHR1) have been implicated in a wide variety of other physiological functions and behaviors, including feeding/metabolism, reward, anxiety, depression, and learning." (PMID 36177357, 2022). "Four genes were associated with both treatment outcomes and these symptom dimensions: CGREF1 (anxiety); MCHR1 (neuroticism); FTO and NRXN3 (sleep)." (PMID 39191930, 2024). "The MCHR1 antagonist SNAP acting on the BLA can relieve stress-induced anxiety and reduce intestinal permeability and inflammation, thus alleviating stress-induced IBS-like symptoms." (PMID 36016574, 2022). "Infusion of MCH was shown to induce anxiety-like responses in an animal model whereas MCH antagonists have been found to be anxiolytic and MCHR1 knockout mice are reported to exhibit lower levels of anxiety-like behavior." (PMID 35327363, 2022). "Rodents treated with systemic MCHR-1 antagonists or that have a genetic knock-out of MCHR-1 exhibit decreased anxiety behavior, including improving performance in forced-swim and social interaction tests." (PMID 25741247, 2015). "The genes CCK, POMC, MCHR1, GABRA6, HTR2A and DRD2, which associated with heat score in at least one brain area, are known to modulate emotional states like anxiety and satiety or even sexual motivation." (PMID 21504592, 2011). "Knockout MCHR1 mice exhibited reduced anxiety-like behavior." (PMID 32292413, 2020). "Such assays inherently measure locomotor outcomes, so the improved performance in these anxiety tests may reflect the general increase in locomotor activity resulting from MCHR-1 blockade." (PMID 25741247, 2015). "These included genes expected to be related to estrous behavior as they influence states like socio-sexual behavior, anxiety, stress and feeding motivation (OXT, AVP, POMC, MCHR1), but also genes whose association with estrous behavior is novel and warrants further investigation." (PMID 21504592, 2011). "In addition, it is notable that MCHR1 antagonists might find an additional usage in the treatment of anxiety and mood disorders for their anxiolytic and antidepressant effects in some animal models." (PMID 25257526, 2014). "The hyper- reactivity of MCHergic circuit might play an important role in inducing anxiety in the CACS mice, which was verified by microinjection of MCHR1 blocker SNAP into the BLA." (PMID 36016574, 2022). "MCH may promote anxiety in humans since MCH levels are lowest during (presumably positive) social interactions, and this has inspired interest in MCHR-1 blockade for treating anxiety disorders." (PMID 25741247, 2015). "Other reports using MCHR-1 antagonists, however, have not confirmed a role for MCH in anxiety suggesting that more work is needed to understand the complex role of MCH in this system." (PMID 25741247, 2015).
depression (10 papers, 2014 to 2024). "The present study investigated whether the role of MCH/MCHR1 in the LC in depression-like behaviors is associated with the regulation of norepinephrine." (PMID 38135278, 2024). "We also verified the correlation between the antidepressant mechanism of MCHR1 antagonism in the LC and NE regulation in the rats that exhibited depression-like behavior induced by microinjection of MCH in the LC." (PMID 38135278, 2024). "MCH has a stimulatory effect on the HPA axis, and our previous study confirmed that antagonizing MCHR1 in the LC reversed depression-like behaviors induced by hyperactivation of HPA axis." (PMID 38135278, 2024). "Another study found that hippocampal MCHR1 gene expression significantly increased in a mouse model of chronic mild stress-induced depression." (PMID 38135278, 2024). "CUS induced an abnormal elevation of MCH levels and downregulated MCHR1 in the LC, which was highly correlated with the formation of depression-like behaviors." (PMID 38135278, 2024). "Meanwhile, we further discovered that the activation of MCH in the LC by CUS and acute microinjection of MCH produced depression-like behaviors by downregulating NE production, which was reversed by the MCHR1 antagonist SNAP-94847." (PMID 38135278, 2024). "Further studies are needed to elucidate the mechanisms of chronic stress- and MCH-induced neuronal dysfunction in the LC to better understand the role of LC MCH/MCHR1 in depression-like behaviors." (PMID 38135278, 2024). "The western-blot analysis of MCHR1 expression in the LC was conducted to verify the antidepressant effect of its antagonism on CUS-induced depression-like behaviors." (PMID 38135278, 2024). "Results obtained with MetaXcan and EpiXcan display the same trend, but only CEWAS found MCHR1 to be common across schizophrenia, bipolar disorder, and depression." (PMID 34807913, 2021). "Specifically, while MCHR1 was also found to be significant for schizophrenia using MetaXcan and EpiXcan, their p-values for bipolar disorder and depression are an order of magnitude higher than the Bonferroni threshold." (PMID 34807913, 2021). "In conclusion, we found that CUS-induced changes in MCH/MCHR1 levels in the LH and LC varied with different stress durations, and MCHR1 antagonism improved depression-like behaviors, suggesting that the MCH system in the LC is indeed closely related to the formation of depression-like behaviors." (PMID 38135278, 2024). "Our findings suggest that MCH/MCHR1 in the LC may be closely related to the onset and progression of depression." (PMID 38135278, 2024). "Our data demonstrated that MCH inhibited noradrenergic synthesis in the LC by acting on MCHR1, which might further diminish the NE projection to the mPFC as an inducement of the depression-like behaviors." (PMID 38135278, 2024). "Based on these results, we hypothesize that maintaining homeostasis of the MCH/MCHR1 system, especially MCHR1 in the LC, is essential for regulating depression-like behaviors." (PMID 38135278, 2024). "The present study used a CUS procedure to investigate the correlation between MCH/MCHR1 in the LC and the formation of depression and whether the mechanism involves the regulation of norepinephrine (NE) in the LC." (PMID 38135278, 2024). "Our study confirmed that the MCH/MCHR1 system in the LC may be involved in depression-like behaviors by downregulating norepinephrine production." (PMID 38135278, 2024). "Our results also suggest that MCH and MCHR1-mediated cAMP-PKA signaling may regulate noradrenaline producing enzymes in the LC and noradrenergic dysregulation may underlie the occurrence of depression-like behaviors." (PMID 38135278, 2024). "To explore whether MCH acts through MCHR1 to induce depression-like behaviors, we investigated the expression of MCHR1 in the LC." (PMID 38135278, 2024). "Our previous study suggested that MCH/MCH receptor 1 (MCHR1) in the LC may be involved in the regulation of depression." (PMID 38135278, 2024).
depression (continued). "Loss of REM sleep associated with clinical insomnia or otherwise insufficient sleep might also potentially be treated by an MCHR1 agonist, but as in depression, it is unclear what benefit this might provide." (PMID 36177357, 2022). "However, the exact mechanism by which MCH/MCHR1 in the LC is involved in modulating depression-like behaviors remains unclear." (PMID 38135278, 2024). "Intraperitoneal administration of the MCHR1 antagonist SNAP-94847 was reported to significantly reverse anxiety- and depression-like behaviors induced by chronic stress." (PMID 38135278, 2024). "Meanwhile, we found that MCHR1 antagonism in the LC restored the CUS/MCH-induced downregulation of MCHR1 expression and ameliorated depression-like behaviors." (PMID 38135278, 2024). "This behavioral effect may be mediated by MCHR1, in which the MCHR1 antagonist SNAP-94847 blocked depression-like behaviors that was induced by MCH." (PMID 38135278, 2024). "In this study, administration of the MCHR1 antagonist SNAP reversed the inhibitory effect exerted by MCH on HFD mice during the sucrose preference test, which aligns with the therapeutic effects observed with MCHR1 antagonists for treating depression." (PMID 39758319, 2024).
schizophrenia (7 papers, 2011 to 2022). A major psychotic disorder characterized by abnormalities in the perception or expression of reality. "Yet, in a large, collaborative study utilizing deep sequencing technology applied to mRNA samples isolated from brain tissue of schizophrenia cases versus controls, MCHR1 expression was significantly decreased in the cases." (PMID 35327363, 2022). "The evolutionary trade-off in this case would have been an increased prevalence of polymorphisms in melanotropin genes (MCHR1, MC5R, MCHR2) of risk for schizophrenia." (PMID 23847488, 2013). "Thus, it is of concern that the decreased expression in schizophrenia cases may have been confounded by smoking-induced hypermethylation of a site in the promoter region of MCHR1." (PMID 35327363, 2022).
vitiligo (7 papers, 2014 to 2023). Generalized well circumscribed patches of leukoderma that are generally distributed over symmetric body locations and is due to autoimmune destruction of melanocytes. "There are highly specific autoantibodies against MCHR1 in vitiligo patients that play an important role in the pathogenesis of vitiligo autoimmunity." (PMID 32703156, 2020). "In some cases, autoantibodies against MCHR1 were found in the serum of vitiligo patients and it has been hypothesized that they can modulate receptor activity." (PMID 33301440, 2020). "Importantly, MCHR1 has been identified as an autoantigen in vitiligo patients." (PMID 25221996, 2014). "Notably, in the serum of patients with vitiligo, autoantibodies against MCH receptor 1 (MCH-R1) were found to block the activity of MCHR1 and the binding of MCH with MCHR1 in a competitive manner." (PMID 35721084, 2022). "Several melanocyte autoantigens have been detected in vitiligo patients including tyrosinase, tyrosinase-related protein 1, tyrosinase-related protein 2, melanosomal matrix protein gp 100 (Pmel17), melanocyte transcription factor (SOX10), and melanin concentrating hormone receptor 1 (MCHR1)." (PMID 29362715, 2017).
bipolar disorder (4 papers, 2013 to 2023). A disorder of the brain that causes unusual shifts in mood, energy, activity levels and the ability to carry out day-to-day tasks. "MCHR1 (originally designated GPR-24) was the most significantly differentially methylated gene in the bipolar disorder (BPD) cases, 90% of whom carried a type 1 diagnosis, often associated with psychosis." (PMID 35327363, 2022). "A potentially relevant example would be the phenotypic plasticity identified in monozygotic twins discordant for bipolar disorder, who carry epigenetic methylation differences in the receptor for the functional antagonist of alpha-MSH, the melanotropin receptor known as GPR24 or MCHR1." (PMID 23847488, 2013).
diabetes (4 papers, 2016 to 2022). "The MCHR1 is involved in the regulation of energy homeostasis and changes of the expression are linked to a variety of associated diseases, such as diabetes and adiposity." (PMID 28808288, 2017). "Since the MCHR1 is primarily involved in the integrated regulation of energy homeostasis, [11C]SNAP-7941 and [18F]FE@SNAP may serve as a useful tool for imaging and therapy monitoring of a broad range of connected disease such as diabetes, adiposity and insulin resistance." (PMID 28808288, 2017).
breast carcinoma (3 papers, 2017 to 2021). "For example, of interest may be the melanin-concentrating hormone receptor (MCHR1) gene, to which both height- and breast cancer risk-associated SNPs were annotated." (PMID 28117334, 2017).
ciliopathy (3 papers, 2020 to 2023). A genetic disorder of the cellular cilia or the cilia anchoring structures, the basal bodies, or of ciliary function. "For example, the melanin-concentrating hormone receptor 1 (MCHR1) and somatostatin type 3 receptor (SSTR3) localize to the axoneme of neuronal cilia and are mis-localized in ciliopathy mouse models." (PMID 33214552, 2020).
colitis (3 papers, 2013 to 2021). Inflammation of the colon. "Anti-MCH antibody suppressed the production of fibrotic genes in experimental colitis, and oral administration of MCHR1 antagonist decreased Col1α1 and TGFβ1 expression levels in a dose-dependent manner in the liver of C57BL/6 J mice with severe hepatic steatosis." (PMID 34912333, 2021). "In experimental colitis, MCHR1 antagonist reduced colonic inflammation, probably by blocking IL10 upregulation, suggesting that inhibition of MCH/MCHR1 signaling could be a novel anti-inflammatory therapeutic approach." (PMID 34912333, 2021). "In relation to MCH, we have found several-fold upregulation of MCH and MCHR1 mRNA expression in the colon of mice with TNBS colitis (unpublished data) and in patients with inflammatory bowel disease, as we report here for their zebrafish orthologs, MCH2 and MCHR1b, respectively." (PMID 24376661, 2013).
melanoma (3 papers, 2019 to 2025). A malignant, usually aggressive tumor composed of atypical, neoplastic melanocytes. "MCH has been found to couple to Gi/o and Gq protein pathways in cell culture models, although the selectivity for each varies among cellular context; in CHO cells and in HEK293 cells MCH causes activation of ERK via both G proteins, but in SK-MEL37 melanoma cells MCHR1 only couples to Gi/o." (PMID 41307117, 2025). "Far fewer of these early studies utilized cell models endogenously expressing MCHR1, but some include models such as human peripheral blood mononuclear cells, SH-SY5Y neuroblastoma cells, SK-MEL37 melanoma cells and murine 3T3-L1 pre-adipocytes." (PMID 41307117, 2025). "Although no direct role for MCH in melanoma has been identified, MCHR1 has been found to be expressed in human melanocytes and melanoma cells, potentially allowing for MCH signaling to occur." (PMID 33301440, 2020).
mood disorder (3 papers, 2014 to 2022). A cognitive disorder a disturbance in which the person's mood is hypothesized to be the main underlying feature. "Thus the effect of MCHR1 antagonists on mood disorders is no longer discussed in this article." (PMID 25257526, 2014).
anxiety disorder (2 papers, 2014 to 2022). A category of psychiatric disorders which are characterized by anxious feelings or fear often accompanied by physical symptoms associated with anxiety. "Both chemogenetic activation of MCH neurons and microinjection of MCH into the BLA induced anxiety disorder in mice, which were reversed by intra-BLA microinjection of MCH receptor 1 (MCHR1) blocker SNAP-94847." (PMID 36016574, 2022).
Bardet-Biedl syndrome (2 papers, 2012 to 2013). A ciliopathy with multisystem involvement. "The obese phenotype seen as a result of primary cilia loss in Bardet-Biedl syndrome is hypothesized to be the result of a loss of cilia-localized MCHR1 in the brain." (PMID 24348551, 2013). "Mchr1, which is a key regulator of feeding behavior, localizes to neuronal cilia in the hypothalamus of wildtype mice but fails to localize to cilia on neurons lacking proteins mutated in the human obesity syndrome Bardet-Biedl syndrome (BBS)." (PMID 23029470, 2012).
inflammatory bowel disease (2 papers, 2012 to 2013). A spectrum of small and large bowel inflammatory diseases of unknown etiology. "We have recently reported that mRNA expression of MCH and MCHR1 are upregulated in the afflicted mucosa of patients with inflammatory bowel disease (IBD)." (PMID 22848656, 2012).
insomnia (2 papers, 2014 to 2022). A sleep disorder characterized by difficulty in falling asleep and/or remaining asleep. "The possible side effects of the clinical use of MCHR1 antagonists include insomnia, hypersexuality, aggression, and hypertension." (PMID 24924345, 2014).
psychosis (2 papers, 2014 to 2022). "MCHR1 exhibited hypomethylation of exon 1 in psychosis subjects from two independent studies, while HNF-1 motifs were found adjacent to CpG sites thought to be associated with alternative splicing." (PMID 35327363, 2022). "In reviewing this research, the focus is on three genes as models for differential methylation, MCHR1, AKT1 and TDO2, each of which have been investigated for genetic association with psychotic disorders." (PMID 35327363, 2022). "The hypomethylation in exon 1 of MCHR1 for psychosis cases, documented by two independent research groups in blood samples, did not correspond well with the reduced brain expression of MCHR1 in psychosis cases, the latter outcome potentially attributable to smoking." (PMID 35327363, 2022). "If so, then the effect of smoking to decrease overall AKT1 methylation but to increase relevant TDO2 and MCHR1 methylation may indeed have functional relevance to psychosis." (PMID 35327363, 2022). "Whereas MCHR1 has repeatedly shown significant genetic linkage to psychotic disorders as a single gene, AKT1 and TDO2 have not in a reproducible manner, yet, that does not preclude these loci from exerting relevant effects as a result of environmentally-induced epigenetic changes." (PMID 35327363, 2022).
Cataplexy (1 paper, 2022). A sudden and transient episode of bilateral loss of muscle tone, often triggered by emotions. "Outside of MCHR1 antagonists for narcolepsy/cataplexy, any other potential clinical applications of drugs targeting the MCH system in the treatment of sleep disorders are entirely speculative." (PMID 36177357, 2022).
colon cancer (1 paper, 2012). "MCHR1 expression was also detected in a human (Caco2) and mouse (MCA-38) colon cancer cell line by immunofluorescence as well as by RT-PCR (data not shown)." (PMID 22848656, 2012).